GATA3 (GATA binding protein 3)
Diseases named in the same sentence as GATA3 in open-access papers (continued):
Sharing a sentence is not in itself a finding about the gene and the disease.
breast carcinoma (continued). "In addition, we identified ER, Bcl-2, Myb, and GATA3 at the center of the good prognostic gene cluster, which matched perfectly with the known clinical and pathologic roles of these molecules in breast cancer." (PMID 23029298, 2012). "Our studies show that TCF7L2 cooperates with the master regulator GATA3 to repress transcription in the well-differentiated MCF7 breast cancer cell line and suggest that a TCF7L2-GATA3 complex may be a critical regulator of breast cell differentiation." (PMID 22951069, 2012). "In addition, we investigated the association of YKL-40 with other two potential biomarkers GATA-binding protein 3 (GATA3) and E-cadherin in breast cancer, both of which correlate with ductal differentiation and a favourable prognosis of breast cancer." (PMID 21934681, 2011). "Moreover, GATA3 (GATA binding protein 3) is reported as a breast cancer marker and is expressed almost among all ER-positive tumors." (PMID 22369133, 2011). "Nevertheless, we identified the tissue level of YKL-40 is correlated positively with another breast cancer marker Her2/neu and negatively with other markers ER, PR, GATA3, and E-cadherin, highlighting the valuable biomarker of YKL-40 in breast cancer diagnosis." (PMID 21934681, 2011). "In the present work, we studied FOXA1 and GATA-3 expression in order to evaluate whether the proteins would predict the recurrence behaviour of breast cancer patients." (PMID 19549328, 2009). "Moreover, in order to quantify the risk of these survival associations, univariate analysis was performed for FOXA1 and GATA-3 as well as for the classical prognostic factors in breast cancer." (PMID 19549328, 2009). "Based on this intricate and functional complex between FOXA1 and GATA-3 in breast cancer biology, it is reasonable to consider that these transcription factors, in addition to ERα, are important in establishing and clarifying the hormone-responsive phenotype and prognosis in breast cancer." (PMID 19549328, 2009). "Similarly, expressed sequence tag database and DNA microarray analyses showed that the GATA3 gene is expressed mainly in breast carcinomas compared with other GATA genes." (PMID 17078870, 2006). "The MCF7 breast cancer cell line displayed the highest GATA3 expression level observed." (PMID 17078870, 2006). "This suggests that GATA3 may contribute to MUC1 upregulation in a subset of breast cancer cells (namely ERα-positive breast carcinoma)." (PMID 17078870, 2006). "We therefore designed the present study to elucidate whether MUC1 expression is regulated by GATA3 in breast cancer cells." (PMID 17078870, 2006). "Our findings suggest that GATA3 could contribute to the transcriptional upregulation of MUC1 gene expression in some breast carcinomas." (PMID 17078870, 2006). "Thus, the aim of this study was to evaluate the role of GATA3 as a putative transcriptional regulator of MUC1 in breast cancer." (PMID 17078870, 2006). "Interestingly, among the GATA family members GATA3 was by far the most frequently expressed GATA transcription factor in breast cancer." (PMID 17078870, 2006). "Moreover, GATA3 may be more helpful in this context, however GATA3 expression can be lost in poorly differentiated breast carcinoma, making situation more complex." (PMID 40025593, 2025). "Leveraging findings from comparative studies, like those examining GATA-3 expression in canine mammary tumors—where it has shown correlations with favorable prognostic factors—can provide additional layers of understanding regarding the potential implications of AR expression in human breast cancer." (PMID 40286049, 2025). "Our discovery that AR and GATA3 cooperate to promote expression of luminal genes is consistent with molecular pathology studies reporting a strong positive correlation between AR and GATA3 expression in breast cancers, even stronger than the correlation between ER and GATA3." (PMID 38317241, 2024).
breast carcinoma (continued). "Similarly, GATA3 expression was positively correlated with BCL2 expression in breast cancer." (PMID 38668712, 2024). "Additionally, we detected high mutation frequencies in TTN and GATA3 across both the high and low ARL score groups, potentially reflecting common biological characteristics of breast cancer and underscoring their importance in breast cancer pathogenesis." (PMID 38189818, 2024). "Conversely, IHC markers for breast cancer (BC) include GATA3, GCDFP-15, TRPS1, estrogen receptor (ER), progesterone receptor (PR), and human epidermal growth factor receptor 2 (HER2)." (PMID 38905573, 2024). "It is unknown how loss-of-function of GATA3 regulates EMT and CSCs in breast cancer." (PMID 37353480, 2023). "Therefore, the role of GATA3 in breast cancer appears to be context specific." (PMID 36909571, 2023). "Epigenetic changes in GATA3 function may thus be relevant to breast cancer biology." (PMID 37564937, 2023). "However, due to the development of kidney cysts and consequential renal failure, as well as various types of tumors in other organs including lymphoma and sarcoma in p18mt;Gata3+/− mice, we were unable to follow the mammary tumor formation and metastasis in aged mice." (PMID 37353480, 2023). "Furthermore, all p18mt;Gata3+/− mammary tumors with metastasis were Fra1-positive." (PMID 37353480, 2023). "We could learn more about the function of GATA3 in breast cancer when clicked on ‘more detail’." (PMID 34986601, 2022). "Furthermore, Notch3 can inhibit EMT in breast cancer epithelial cells by transactivating GATA3." (PMID 36139447, 2022). "Therefore, it is still unclear whether these slight differences in the GATA3 protein structure can produce different outcomes in luminal breast cancer." (PMID 35154280, 2022). "We describe a blood-based breast cancer detection test based on functional enrichment of breast-adenocarcinoma-associated circulating tumor cells (BrAD-CTCs) and their identification via multiplexed fluorescence immunocytochemistry (ICC) profiling for GCDFP15, GATA3, EpCAM, PanCK, and CD45 status." (PMID 35884402, 2022). "Finally, we validate that FOXA1 and GATA3 mediate hypo-methylated regions in breast cancer cells." (PMID 35331302, 2022). "An altogether different type of pattern was discovered within GATA3 in breast cancer where we found that GATA3 mutations not included in the best found subgroupings tended to have predicted scores between those assigned to samples carrying the subgrouping and GATA3 wild-types." (PMID 33957863, 2021). "Thus, their interaction with cancer related axes including FOXM1/GATA3/FOXA1/ESR1 axis might affect the course of breast cancer." (PMID 34094972, 2021). "Therefore, we speculated that GATA3 may play a promoting role on the occurrence of ER+ breast cancer by regulating the TME and ER transcription." (PMID 32538432, 2020). "Other genes, such as ESR1 (logFC 6.02); GATA3 (logFC 3.88); ERBB4 (logFC 3.0); AR (logFC 2.94); CCDC170 (logFC 2.79); MAPT (logFC 2.45); PGR (logFC 2.91); PIP (logFC 5.42) in immunoglobulin G-binding protein from this cluster were closely associated with breast cancer progression." (PMID 32182819, 2020). "Thus, GATA‐3 presents an appropriate marker for identifying the TNBC subset of breast cancers." (PMID 33133558, 2020). "Furthermore, ER binds near the GATA3 gene in breast cancer cells, as shown through ChIP assays." (PMID 31408468, 2019). "Thus, our findings provide novel insights into the GATA3's inhibition of breast cancer metastasis." (PMID 31754326, 2019). "Besides, interaction of FOXN3 with NEAT1/SIN3A showed to repress GATA3 in breast cancer metastasis." (PMID 30894512, 2019).
breast carcinoma (continued). "Importantly during breast cancer development, GATA3 indeed has a tumor suppressor function." (PMID 27374105, 2016). "This analysis confirms previous findings that FOXC1 and GATA3 are involved in a switch between basal-like and luminal-like expression programs in breast cancer, and indicates that the high-resolution time-series data may identify novel factors that underlie this switch." (PMID 27539783, 2016). "Interestingly, 4 of 14 p18−/−;Gata3+/− mice with lymphomas also developed mammary tumors." (PMID 27588406, 2016). "In addition, low levels of GATA3 correlate with decreased breast cancer patient survival." (PMID 26097693, 2015). "In addition, consistent with a previous study on breast cancer, ectopic expression of GATA3 could also inhibit TGF-β1-induced EMT in 22RV1, as evident by increased E-cadherin expression and decreased Vimentin and Snail expression." (PMID 26451614, 2015). "Furthermore, deregulation of BCL2, DACH1 and THSD4 may represent key events accompanying GATA3-mediated transformation of normal cells into breast cancer." (PMID 25410484, 2014). "The expression of GATA3 is strongly associated with estrogen receptor (ER) expression in breast cancer and there is accumulating evidence that GATA3 may be used as a clinical marker to determine response to hormonal therapy and refine the prognosis of breast cancer patients." (PMID 24748983, 2014). "In breast cancer patients, GATA3 expression displays a steady decrease with increasing tumor grade, and several independent studies demonstrated that GATA3 expression holds independent prognostic value, with increased GATA3 expression correlating with good prognosis." (PMID 25479686, 2014). "To study GATA3-associated mechanisms involved in normal cell functions and luminal breast cancer, we selected genes (from those identified by ChIP-seq), representing different molecular processes according to the GO browser, and their response to GATA3 was examined in hMEC and in MCF7 cells." (PMID 25410484, 2014). "Thus, GATA3 may also influence the TGFß response in breast cancer cells by influencing the response through C/EBP transcription factors." (PMID 23577196, 2013). "Analysis of transcript co-regulation in our samples showed that additional genes are expressed in parallel with GATA3, including those coding for carbonic anhydrase XII (CA12), cyclin D1 (CCND1) or hepsin (HPN), all of which have been associated with breast cancer." (PMID 24205108, 2013). "GATA3 is one member of a transcription factor family that plays an essential role in the specification of and maintenance of differentiated cell types, in particular in mammary gland differentiation and in breast cancer has emerged as a strong predictor in tumour differentiation." (PMID 19828084, 2009). "In fact, in a case like ours, additional immunohistochemical markers were performed (such as, GATA‐3, calretinin, TTF‐1) for the diagnosis of breast cancer." (PMID 41239938, 2026). "Two studies on TRPS1 in metastatic breast cancer cytological samples indicated that the positivity rates of TRPS1 and GATA3 were similar (7/9 vs. 6/9; 5/7 vs. 5/7)." (PMID 40822238, 2025). "It is notable that TRPS1 positivity was 100% in all special type breast cancers in this cohort, including metaplastic carcinoma, whereas the positivity rate of metaplastic carcinoma was low with SOX10 and GATA3." (PMID 40025593, 2025). "Research indicated that the transcriptional regulatory network involving estrogen receptors alpha (ESR1), GATA3, and FOXA1 plays a significant role in the development of breast cancer." (PMID 40003882, 2025). "In breast cancer, EZH2 maintains luminal progenitor cells and restricts their differentiation by repressing enhancers of GATA3, a key TF driving luminal cell differentiation." (PMID 40032852, 2025).
breast carcinoma (continued). "Finally, a significant anti-correlation between the expression levels of GATA3 and DNMT3B, initially observed in the TCGA–BRCA dataset, was confirmed in our validation cohort, suggesting that GATA3 may indeed be down-regulated by the aberrant activation of DNMT3B in breast cancer." (PMID 40585280, 2025). "Breast cancer tissue specimens typically exhibit positive results for CK7, GATA-3, GCDFP15, and SCGB2A2, with approximately 30% of OBCs testing positive for estrogen receptor (ER) and progesterone receptor (PR), while 40% are negative." (PMID 40474021, 2025). "For example, GATA3 influences immune cell infiltration and function within the TME, modulating anti-tumor immunity in breast cancers." (PMID 41514651, 2025). "The results revealed elevated levels of several breast cancer-related genes, including AZGP1, GATA-3, KRT14, XIST, and ESR1." (PMID 40474021, 2025). "The gene detection results demonstrated elevated levels of breast cancer-related genes, including AZGP1, GATA-3, KRT14, XIST, and ESR1." (PMID 40474021, 2025). "To further confirm the overlap between GATA3 and CHD4 in breast cancer cells, we performed CHD4 ChIP-seq in T47D cells, where both CHD4 and GATA3 are endogenously expressed." (PMID 38281186, 2024). "While TRPS1 is expressed in a wider range of breast cancer subtypes, the use of SOX10 is generally limited to specific TNBC cases, often as part of a broader panel including GATA3 and CK5/6." (PMID 39518009, 2024). "GATA-3 staining has been correlated with both PCAANOS/sweat gland carcinoma and cutaneous metastasis of breast carcinoma, with one study finding nuclear positivity in 71% and 91%, respectively." (PMID 39185026, 2024). "A panel made out of a novel marker, MGP, used together with GATA3 and TRPS1 can lead to an increased sensitivity in the recognition of all breast carcinomas." (PMID 39518009, 2024). "Among the 34 380 GATA3 peaks that we had previously defined, CHD4 signals were observed at 16 225 GATA3 peaks (47%), confirming the frequent overlap between CHD4 and GATA3 in luminal breast cancer cells." (PMID 38281186, 2024). "With GATA3 and TRPS1, more specific breast cancer markers are available that showed 55.4% (GATA3,) and 77.8% positivity (TRPS1, manuscript in revision) in triple-negative breast cancers in our tumor cohort." (PMID 38790919, 2024). "We have shown that LSD1 suppresses breast cancer metastasis by inhibiting the expression of tripartite motif containing 37 (TRIM37) and inducing the transcription of GATA binding protein 3 (GATA3)." (PMID 38448424, 2024). "While hormone receptors, mammaglobin, GATA3, and, in some cases, SOX10 remain the primary markers for most subtypes of breast carcinoma, TRPS1 has proven particularly useful in cases where these markers are either absent or equivocal." (PMID 39518009, 2024).
breast carcinoma (continued). "Breast cancer and SDC show similar expressions of several biomarkers, such as mammaglobin, GATA3, estrogen receptor (ER), HER-2, PI3KCA, and HRAS." (PMID 38539538, 2024). "Most GATA3/FOXA1 studies, mostly focusing on breast cancer, demonstrated that the combination of the two indicators can better predict the prognosis than either indicator alone." (PMID 38425344, 2024). "The protein complex GATA3/G9A/MTA3 represses ZEB2, and other genes involved in EMT, leading to suppression of metastasis from human breast cancer cells in mice." (PMID 39242600, 2024). "Genomics data found that GATA3 binds to the P4HTM locus, and that ectopic expression of GATA3 in basal breast cancer cells increases the P4HTM transcript level." (PMID 36909571, 2023). "It strengthened the tolerance of breast cancer to DOX via binding and recruiting NF-κB to promote GATA3 transcription, further leading to the activation of STAT3." (PMID 37781691, 2023). "For example, GATA3, ESR1, and TRPS1 were identified as the three leading master regulators in breast cancer." (PMID 37600846, 2023). "The level of GLS2 protein in breast cancer cell lines correlated with that of the GATA3 transcription factor; a positive correlation between the GLS2 and GATA3 transcript levels was found in human breast cancer tissues." (PMID 38067269, 2023). "In 2 cases, the presence of ERBB2 duplication prompted additional immunohistochemical analysis with mammaglobulin, GATA3, and GCDFP, which ultimately led to diagnosis of HER2 positive breast carcinoma." (PMID 36933203, 2023). "Further studies on GATA-3 and GCDFP-15 would be recommended in the future using more cases and different types of breast cancer." (PMID 37383162, 2023). "The SIN3A-HDAC complex is recruited to the promoter of GATA3 by FOXN3 to repress GATA3 expression, thus repressing breast cancer metastasis." (PMID 37291119, 2023). "In women, the degree of tumoral differentiation may result from the interaction of GATA-3 with the BRCA1 gene, which cause the formation of protein complexes that suppress genes associated with the triple negative basal-like phenotype (ER−, PR−, HER-2−, and CK 5/6+ or CK14+) in breast carcinomas." (PMID 37483298, 2023). "Previous studies demonstrated anti-metastatic effects of Notch3, a transcription factor, through transcriptional up-regulation of p21, estrogen receptor-α (ERα), GATA-3, miR-488/FSCN1 and Kibra-mediated Hippo/YAP signaling in breast cancer epithelial cells." (PMID 38124049, 2023). "In the present study, we have demonstrated that heterozygous germline deletion of Gata3 up-regulates Fra1, downregulates c-Fos, activates EMT, and enhances mammary tumor initiating and metastatic potential." (PMID 37353480, 2023). "The pathology of the thyroid samples disclosed a secondary malignancy of poorly differentiated breast cancer with immunophenotypes CK7+, CK 20-, GATA3+, TTF-1-, P40-, S100-, CDX-2-, Thyroglobulin-, Pax8-, and P63-." (PMID 37048792, 2023). "A similar downregulation of GATA3 was also observed in mice that express oncogenic KRAS and develop basal-like and claudin-low (mesenchymal-like) mammary tumors." (PMID 38067308, 2023). "The upregulation of luminal progenitor markers (GATA3, CD61) in response to the suppression of oncogenic RAS signaling is validation that claudin-low mammary tumors originated from luminal epithelial cells." (PMID 38067308, 2023).